FGFR1 (fibroblast growth factor receptor 1)
Diseases named in the same sentence as FGFR1 in open-access papers (continued):
Sharing a sentence is not in itself a finding about the gene and the disease.
breast cancer (continued). "FGFR1 amplification is known to have meaningful association with worse prognosis among breast cancer patients, in particular those with ER-positive cancers." (PMID 31754359, 2019). "Evaluating the genetic alterations from METABRIC and TCGA datasets, we then assessed that FGFR1 is the most frequently amplified FGFRs family member and its amplification/expression associates with shorter survival rates in breast cancer patients." (PMID 30866584, 2019). "Formation of N-cadherin complexes with FGFR1 in breast cancer cells causes decreased internalization and lysosomal degradation of FGFR1, and sustained receptor signaling via MAPKs." (PMID 31091809, 2019). "Of note, breast cancer patients with either higher expression or copy number (CN) gains of FGFR1 are associated with shorter overall survival rates respect to the rest of the cohort." (PMID 30866584, 2019). "Possible clinical settings for testing such combinations (always in FGFR1-amplified patients) include an advanced disease setting and in patients with high-risk early breast cancer in an adjuvant setting." (PMID 31126332, 2019). "Although active Ras mutations and FGFR1 amplification and overexpression barely occur in the same breast cancer cells, FGFs are always present in the tumor microenvironment and FGFRs are expressed in breast epithelial and cancer cells." (PMID 30111373, 2018). "FGFR1 amplification is present in 20% of squamous cell lung cancer, 5% of small cell lung cancer and in 10% of breast cancers, FGFR2 amplifications or mutations in about 5% of gastric cancer, FGFR3 mutations in 10-15% of muscle invasive bladder cancer." (PMID 30181810, 2018). "About 14% of breast cancer patients bear mutations in the 8p11-12 chromosomal region, which is a site harboring the FGFR1 gene locus." (PMID 30011957, 2018). "All the results show that individuals with the C allele of FGFR1 rs2420946 presented a greater risk of overall toxicity for CET chemotherapy in breast cancer (adjusted OR = 1.65, 95% CI = 1.11–2.46, P = 0.013)." (PMID 30359238, 2018). "To conclude, we have shown that high Shannon indices of c-MYC and FGFR1 copy number variation are associated with adverse features of breast cancer." (PMID 29228597, 2017). "Breast cancer patients with FGFR1 amplification had a 460% higher risk of mortality (95% confidence interval, 2.172-87.28; log-rank test) than those without FGFR1 amplification." (PMID 28125801, 2017). "FGFR1 protein expression of ≥1% in tumors was associated with poor survival in patients with breast cancer." (PMID 28056982, 2017). "FGFR1 amplification was also associated with poor survival in esophageal cancer, breast cancer, and squamous-cell lung cancer." (PMID 28056982, 2017). "In breast cancer, FGFR1 amplification has been associated with endocrine resistance and poor prognosis." (PMID 28030802, 2017). "Little has been reported regarding the clinicopathologic and biomarker association of FGFR1 protein expression in breast cancer." (PMID 26673008, 2016). "Amplification of FGFR1 occurs in 10% of ER positive cancer, enriched in luminal B type breast cancer, with FGFR1 amplification associating with increased risk of relapse." (PMID 25932042, 2015). "Approximately 10 % of breast cancers have FGFR1 amplification and its amplification is associated with early relapse, poor survival and drug resistance." (PMID 26581390, 2015). "FGFR1 amplification has been identified in around 10 % of HR+ breast cancers, and it has been associated with a worse prognosis, higher Ki67 expression, and resistance to endocrine therapy." (PMID 26059247, 2015). "The Fibroblast Growth Factor Receptors can be activated by diverse mechanisms in breast cancer, including amplification of FGFR1 and FGFR2, rare activating mutations and translocations, as well as potentially through aberrant ligand dependent signaling." (PMID 25932042, 2015).
breast cancer (continued). "Some of other types of cancer such as oral squamous carcinoma, esophageal squamous cell carcinomas, breast cancer and pancreatic cancer have also been reported to be associated with FGFR1 amplification." (PMID 25171497, 2014). "Aberrant FGFR activity is also involved in the progression of breast cancer, in particular, FGFR-1 upregulation associates with early relapse and poor survival in breast cancer patients." (PMID 24743893, 2014). "Of note the FGFR1 which has been implicated in hormonal resistance in ER+ breast cancer, is present at the edges of the 8p11.2 amplicon, but is not present in our minimal amplicon defined by our analysis." (PMID 22719901, 2012). "Specifically, FGFR1 is amplified in approximately 10% of breast cancer and is associated with early relapse and poor patient survival." (PMID 23029290, 2012). "In FGFR1, expression of truncated splice variants such as FGFR1β, which lacks the first Ig-like domain, enhances ligand binding affinity and mitogenic signaling and has been associated with aggressive behavior in breast cancer and other solid tumors." (PMID 41514604, 2025). "All the point mutations in FGFR1 occurred in hotspot amino acids (p.Asn546Lys, p.Asn546Asp, p.Lys656Glu) that have previously been reported in many cancer types, including glioma and breast carcinoma." (PMID 40016412, 2025). "The FGFR1 is an amplified oncogene associated with the early evolution of breast cancer clones." (PMID 37546410, 2023). "In more than 15% of breast cancers with hormone receptors present, a mutation of FGFR1 is found." (PMID 36900131, 2023). "In previous studies FGFR1 gene alterations have been observed in ~ 7-27% of all breast cancers, have been associated with poor prognosis, and constitute a critical mechanism underlying the development of treatment resistance to endocrine suppression via AIs and SERMs." (PMID 37361577, 2023). "FGFR1 amplification was positively associated with luminal B breast cancer." (PMID 35494043, 2022). "In the case of FGFRs, the presence of activating gene mutations in the FGFR axis, of various forms, has been reported in up to 18% of breast cancers, including FGFR1 and FGFR2 amplifications, point mutations in the ligand-binding region and oncogenic fusion proteins." (PMID 35193394, 2022). "FGFR1 amplification was previously shown to be associated with resistance to endocrine therapy, shorter time to distant metastasis, and shorter overall survival in HR+ breast cancer." (PMID 34642262, 2021). "Therefore, based on all the expression and statistical analyses in discovery cohorts, we further established the potential prognostic association of GLI1 and FGFR1 genes using normal and tumor pairs of 150 breast cancer patients." (PMID 34722544, 2021). "However, only a few SNP loci are confirmed in FGFR1 that correlate significantly with a breast cancer predisposition." (PMID 34830836, 2021). "However, it has been observed that FGFR1 upregulation causes resistance to CDK inhibitors in subtypes of breast cancer patients, suggesting alternate treatment strategies." (PMID 34722544, 2021). "In contrast, a more recent study correlated three FGFR1 SNPs to reduced breast cancer risk." (PMID 34830836, 2021). "For instance, a recent study showed that MAP3K1 mutation may improve the prognosis of breast cancer patients with FGFR1 overexpression." (PMID 34722544, 2021). "Interestingly, 8p11.2 gene FGFR1, implicated in hormonal resistance in ER+ breast cancer, had a significant SV-expression association but one that was dependent on amplification." (PMID 34788622, 2021). "However, recent studies showed that FGFR1 upregulation causes resistance to cyclin-dependent kinase (CDK) inhibitors in different breast cancer subtypes." (PMID 34722544, 2021). "In breast cancer, for example, FGFR1 is mutated in ~15% of patients." (PMID 33535617, 2021).
breast cancer (continued). "Furthermore, in primary breast cancer, Jak2 mRNA has a positive association with both LepR (R = 0.61) and FGFR1 mRNA (R = 0.49)." (PMID 33019728, 2020). "In addition, breast cancer cell lines with FGFR1 amplification harbor endocrine resistance that can be reversed by RNA silencing, and FGFR1-amplified breast cancers have been reported to be associated with a poorer prognosis." (PMID 32852708, 2020). "Moreover, FGFR1 has been found highly amplified in breast cancer patients and associated with endocrine resistance." (PMID 30866584, 2019). "Next, we examined differential expression of FGFR1 splicing variants in breast cancer cell lines." (PMID 30713601, 2019). "For example, in hormone receptor-positive, HER2neu-positive, and triple-negative forms of breast cancer, FGFR1 amplification is associated with early relapse and poor outcomes and also promotes the resistance of luminal B type breast cancer to endocrine therapy." (PMID 30326595, 2018). "Similarly, SNPs affecting FGFR2b expression have been correlated with breast cancer susceptibility and amplification of FGFR1, occurring in up to 12% of breast cancer cases, is correlated with poor prognosis." (PMID 30405704, 2018). "However, the FGFR signaling pathway regulates normal mammary gland development and FGFR1 overexpression has been associated with breast cancer progression." (PMID 28775339, 2017). "Indeed, FGFR1 is frequently amplified or mutated in prostate adenocarcinoma (23%), lung squamous carcinoma (23%) and breast cancer (14.3%) (TCGA), and FGFR inhibitors are being trialled clinically." (PMID 27236187, 2016). "FGFR1 activation has shown to induce proliferation in breast cancer; thus its expression could have a direct cause-effect on increased Ki67 rather than merely an epiphenomenon." (PMID 26673008, 2016). "In addition, FGFR1 amplification was associated with distant metastasis, early relapse and poor survival, and contributed to poor prognosis in luminal breast cancers by driving anchorage independent proliferation and endocrine therapy resistance." (PMID 26673008, 2016). "Importantly, increased expression of the β isoform of FGFR1 has previously been associated with breast cancer." (PMID 24618085, 2014). "FGFR1 at 8p12 encodes a tyrosine kinase receptor belonging to the fibroblast growth factor and growth factor receptor family, which is amplified in 9 to 15% of breast cancers." (PMID 22863309, 2012). "Fibroblast growth factor receptor-1 (FGFR1), recently identified as a putative driver of endocrine resistance in breast cancer, is at the edges of the 8p11.2 amplicon that we found associated with early relapse in ER+ breast cancer treated with tamoxifen." (PMID 22719901, 2012). "FGFR1 amplification is associated with a poor prognosis in breast cancer." (PMID 22863309, 2012). "Indeed, FGFR1 itself has been linked with tamoxifen resistance in breast cancer and cisplatin resistance in ovarian cancer." (PMID 21952621, 2011). "Although several growth factor receptors, such as epidermal growth factor receptor, ErbB2 and FGFR1, have been studied and implicated in breast cancer, we are only beginning to understand how these growth factor pathways interact with other autocrine or paracrine factors to promote tumourigenesis." (PMID 19393083, 2009). "Furthermore, FGFR1 is amplified in 10% of human breast tumours and has been linked to a poor response to treatment in breast cancer patients." (PMID 19393083, 2009). "Besides regulating cell proliferation, the FGFR1-dependent activation of ERK1/2 is implicated in epithelial to mesenchymal transition (EMT) by stabilizing the transcription factor Twist in HER2-positive breast cancers." (PMID 35193394, 2022).
breast cancer (continued). "Our findings of FGFR1-induced palbociclib resistance, promotion of cancer stem cells and associated molecular changes advance our mechanistic understanding of CDKi resistance, which will facilitate the development of strategies targeting CDKi resistance in breast cancer treatment." (PMID 34831231, 2021). "Astrocytic FGF2-mediated paracrine activation of FGFR1 promotes breast cancer brain metastasis in estrogen-treated young mice, but FGF2 levels and signaling decrease in the brain with aging and estrogen-depletion." (PMID 42209519, 2026). "In the R/M breast cancer cohort, the distribution of mutations in ERBB2, CDK12, and FGFR1 were similar to those in primary breast cancer." (PMID 40182039, 2025). "FGFR1 amplifications are detected in 7.5% to 17% of all breast cancer cases, with rates rising to 16% to 27% in aggressive HR+ luminal-B tumors." (PMID 40510030, 2025). "By activating of the FGFR1-MEK-ERK2-c-FOS signaling axis, FOXQ1 expression is upregulated, FOXQ1 is an essential factor mediating the FGFR1 signaling and promotes breast cancer worsening." (PMID 41347087, 2025). "Dysregulation of FGFR1 has been observed in several cancers, including lung cancer, breast cancer, renal cell carcinoma (RCC), and head and neck tumors, where its overexpression is often associated with poor prognosis." (PMID 40547805, 2025). "Overactivation of FGFR signaling was also observed in CDK4/6is-resistant breast cancer, with FGFR1/2 overexpression or amplification correlating with reduced sensitivity." (PMID 40244377, 2025). "The calculated combination index (CI) further confirms the synergy between alpelisib and AZD4547, supporting a co-targeting approach to overcome the limitations of single-agent alpelisib in FGFR1-overexpressing breast cancers." (PMID 40510030, 2025). "The most common genetic alteration involving FGFR1 is copy number gain, which is known to occur in a significant subset of breast cancer, non-small cell lung cancer and urothelial cancer." (PMID 41202566, 2025). "FGFR1 amplifications are very common in many cancer types, including lung and breast cancer, whereas FGFR2-4 amplifications are less frequent, yet occurring e.g. in gastric and breast cancer." (PMID 40016412, 2025). "Using paired isogenic MCF-7 breast cancer sublines with differing FGFR1 status, we demonstrated FGFR1-induced resistance to alpelisib and characterized molecular changes in the dysregulated crosstalk between RTK and ER pathways." (PMID 40510030, 2025). "FGFR1 amplifications are present in approximately 8.47% of breast carcinoma patients and predict endocrine treatment resistance in HR-positive breast cancer." (PMID 41590338, 2025). "FGFR1 in breast tissue (particularly in breast cancer) drives cell proliferation, survival, and angiogenesis, thus influencing tumor growth and progression." (PMID 40707586, 2025). "To validate our findings from MCF-7 cells, we extended our investigation to T47D breast cancer cells, a well-characterized luminal breast cancer cell line, using the stable T47D/C and T47D/FGFR1 cell lines previously generated in our laboratory." (PMID 40510030, 2025). "ER+ breast cancer patients with high FGFR1 mRNA expression at baseline show resistance to a CDK4/6 inhibitor + letrozole and had a poor prognosis in the MONALEESA-2 study." (PMID 40227585, 2025). "Taken together, these findings underscore the importance of supporting the therapeutic strategy of co-targeting FGFR1 to enhance the overall efficacy of alpelisib in breast cancer cells." (PMID 40510030, 2025). "This supports the effectiveness of co-targeting PI3K and FGFR1 to overcome alpelisib resistance in FGFR1-overexpressing breast cancer cells." (PMID 40510030, 2025). "In this study, we investigated the effect of FGFR1 overexpression on alpelisib resistance and its underlying mechanisms in MCF-7 and T47D breast cancer cells, two luminal subtype cell lines." (PMID 40510030, 2025).
breast cancer (continued). "In summary, our findings establish FGFR1 as a key driver of alpelisib resistance in ER+ breast cancer by sustaining PI3K/Akt and MAPK/Erk1/2 signaling." (PMID 40510030, 2025). "Results from this study support the role of FGFR1 overexpression or activation in alpelisib resistance in breast cancer treatment." (PMID 40510030, 2025). "FGFR1 alterations, including overexpression, amplification, and functional activation, play a crucial role in breast cancer pathogenesis, particularly in HR+ subtypes." (PMID 40510030, 2025). "Many researches have found that FGFR1 plays a key role in multiple cancers in humans, including breast cancer and colorectal cancer." (PMID 41001045, 2025). "Key pathways such as PI3K-Akt signaling, MAPK signaling, and breast cancer are linked with multiple targets including BRCA1, FGFR1, IGF1, AKT1, and EGF, suggesting their potential involvement in breast cancer pathology influenced by PCBs exposure." (PMID 40584614, 2025). "The MCF-7 breast cancer cell lineexpresses very low levels of FGFR1, and we therefore also used a previouslygenerated MCF-7 cell line stably overexpressing FGFR115 (MCF7-FGFR1)." (PMID 39989790, 2025). "In breast cancer, FGFR1 amplification is enriched in hormone receptor-positive (ER+) subtypes, particularly Luminal B-like (high-proliferation HR+) tumors, and closely associates with endocrine therapy resistance and poor prognosis." (PMID 41514604, 2025). "In this study, we aim to investigate the effect of FGFR1 overexpression on alpelisib resistance in breast cancer cells." (PMID 40510030, 2025). "More clinical studies are needed to explore the role of FGFR1 overexpression/amplification in estrogen sensitivity in ER+ breast cancer." (PMID 40182039, 2025). "FGFR1 amplification also appears in approximately 10% of breast cancers, driving increased ligand-dependent signaling, suppressing progesterone receptor expression, and correlating with poor prognosis." (PMID 40547805, 2025). "Similar to a previous study, FGFR1 gene amplification was identified in approximately 15% of patients with ER+ breast cancer." (PMID 40182039, 2025). "To confirm the functional role of FGFR1 in mediating alpelisib resistance across luminal breast cancer models, we performed siRNA-mediated FGFR1 knockdown in T47D/FGFR1-overexpressing cells (TF)." (PMID 40510030, 2025). "To validate this discovery in the TCGA ER + breast cancer patients, we analyzed the association between FGF2 and FGFR1 expression and pathway signature scores related to cancer stemness and JAK-STAT pathways." (PMID 38553760, 2024). "The amplification of FGFR1 represents the most frequent genomic alteration in breast cancer, with FGFR2-4 gene amplifications being less commonly seen." (PMID 38255923, 2024). "About 10–15% cases of breast cancers involve FGFR1 amplification, especially in hormone receptor-positive and HER2-negative subtypes." (PMID 39796710, 2024). "FGFR1 amplification is also shown to be responsible for the resistant mechanisms to endocrine therapy in breast cancer via both aberrant ligand-dependent and ligand-independent signaling." (PMID 38255923, 2024). "Prolonged estrogen deprivation in breast cancer cells can lead to upregulation of FGFR1 together with FGF3, FGF4, and FGF19 due to co-amplification of the FGFR gene and genes located in the 11q13 region." (PMID 38255923, 2024). "Amplification and overexpression are associated with resistance to estrogen receptor-targeted therapy in luminal breast cancer and indicate a regulatory connection of FGFR1 and estrogen signaling." (PMID 38481600, 2024). "FGFR1 amplification in 12.5% of breast tumors makes ER + breast cancer patients resistant to CDK4/6 inhibitors and endocrine treatments, increasing their likelihood of disease recurrence." (PMID 38831455, 2024).